FOXQ1 (forkhead box Q1)
Diseases named in the same sentence as FOXQ1 in open-access papers (continued):
Sharing a sentence is not in itself a finding about the gene and the disease.
gastric cancer (15 papers, 2012 to 2025). A primary or metastatic malignant neoplasm involving the stomach. "We demonstrate that FOXC2 and FOXQ1 areboth associated with gastric cancer progression.Therefore, both may potentially be used as targetsfor prognosis of patients." (PMID 28580309, 2017). "It has been shown that FOXQ1 expression is increased in gastric cancer cells co-cultured with the monocytic cell line THP-1, and that high numbers of monocytes are associated with elevated FOXQ1 levels in samples from patients with gastric cancer." (PMID 39777582, 2025). "A recent study indicated that the expression of FOXQ1 was so high in gastric cancer cells that it greatly promoted proliferation, migration, invasion, and EMT." (PMID 34299149, 2021). "Further study suggested that FOXQ1 was directly regulated by miR-519 which was observed weakly expressed in both gastric cancer tissues and cells." (PMID 34299149, 2021). "The functional relevance of FOXQ1 in multiple human cancers, such as gastric cancer, esophageal cancer, PDAC, carcinoma of the breast, carcinoma of lung, adenoma, and carcinoma of the intestine, has been appreciated in the recent scientific literature." (PMID 34959269, 2021). "It has been reported that miR-96-5p is downregulated in gastric cancer tissues and inhibits the proliferation, migration, and epithelial-mesenchymal transition of gastric cancer cells by targeting FOXQ1." (PMID 34957298, 2021). "In other words, miRNA-519 functioned as a suppressor in regulating gastric cancer EMT by targeting FOXQ1." (PMID 34299149, 2021). "Other researchers have revealed that miR-1271, miR-345 and miR-519 inhibited FOXQ1 in gastric cancer." (PMID 33098639, 2020). "It has been documented that FOXQ1 can facilitate the metastasis of gastric cancer cells through upregulation of Snail." (PMID 30678643, 2019). "Not surprisingly therefore, high expression level of FOXQ1 was observed to be associated with poor prognosis in gastric cancer patients." (PMID 34708244, 2022). "Furthermore, high expression of FoxQ1 was also observed in lung cancer, gastric cancer, and colon cancer cell lines." (PMID 23383267, 2013). "However, high expression of the FoxQ1 gene was also observed in lung cancer, gastric cancer, and colon cancer cell lines." (PMID 22761930, 2012). "Additionally, FOXQ1 was also found to regulate EMT in gastric cancer cells." (PMID 34708244, 2022). "Furthermore, the impact of FoxQ1 on promoting tumor cell proliferation was also well established in other solid tumors including ovarian cancer, neuroblastoma, lung cancer, gastric cancer, and liver cancer." (PMID 33330033, 2020). "miR-96-5p inhibits the protein expression of FOXQ1 suppresses the proliferation, migration, and EMT of gastric cancer cells." (PMID 41347087, 2025).
lung carcinoma (11 papers, 2012 to 2025). "Our results demonstrated that FoxQ1 expression was significantly associated with EMT in lung cancer cells as well as the TMA of tumor models." (PMID 25356753, 2014). "Previous study has shown that miR-133 exhibits tumor inhibition by directly binding FOXQ1 in lung cancer." (PMID 35600345, 2022). "FOXQ1 is also upregulated in lung cancer and thyroid carcinoma and has been related to poor prognosis." (PMID 36118871, 2022). "For instance, downregulation of EGFR, Forkhead box C1 (FOXC1) and Forkhead box Q1 (FOXQ1) by miR-133 was thought to mediate reduced cell proliferation, migration and invasion of prostate cancer 14, pituitary adenoma 22 and lung cancer 23, respectively." (PMID 34335946, 2021). "In lung cancer cells, elimination of FOXQ1 affected the re-expression of epithelial markers and decreases mesenchymal markers in vitro and in vivo." (PMID 29050264, 2017). "Moreover, downregulated FoxQ1 expression promoted apoptosis of lung cancer cells and the apoptosis induced by cisplatin." (PMID 25356753, 2014). "FoxQ1, a member of the forkhead transcription factor family, is a well-characterized candidate oncogene located on chromosome 6p23-25 that plays an important role in the etiology of human cancer, especially in lung cancer." (PMID 25356753, 2014). "At the cell level, the CCLE database suggested that FOXQ1 was expressed in 1,057 cell lines from 36 tumors, with the background expression level high in pancreatic adenocarcinoma, liver hepatocellular carcinoma, colon adenocarcinoma, lung cancer, and thyroid carcinoma." (PMID 36118871, 2022). "Although the overexpression of FOXQ1 in cancer cell lines confirmed that the gene might play a role in the development of lung cancer, the correlation between FOXQ1 expression and EMT factors to determine its clinical significance in NSCLC has not been previously reported." (PMID 22761930, 2012). "miR-133 also downregulates FOXQ1 expression to mediate the EMT and antagonizes lung cancer tumorigenesis." (PMID 41347087, 2025). "FoxQ1 depletion in SPC-A-1-FoxQ1 and NCI-H1395-FoxQ1 cells contributed to increased apoptotic response to various levels of chemotherapeutic reagents commonly used in lung cancer, including GEM, DDP, DOX, and PEM (A: P=0.003 and B: P=0.007, part data not shown)." (PMID 25356753, 2014). "FOXQ1 overexpression did not influence overall or recurrence free survival in CRC patients; this is in contrast to data from breast and lung cancer patients where FOXQ1 was associated with worse survival." (PMID 23555880, 2013).
bladder cancer (10 papers, 2013 to 2025). "FOXQ1 expression also was associated with an EMT signature in bladder cancer cells and silencing of FOXQ1 increased E-cadherin expression, decreased vimentin expression and attenuated invasive behavior." (PMID 24312263, 2013). "Upregulation of the forkhead box protein Q1 (FOXQ1) promotes bladder cancer (BCa) cell growth and metastasis." (PMID 33098639, 2020). "Similarly, long noncoding RNA-activated FOXQ1 epitopes promote bladder cancer cell expansion and migration." (PMID 41347087, 2025). "Similarly, in bladder cancer, miR-140-3p hinders cancer cell proliferation and invasion by directly targeting FOXQ1." (PMID 38285101, 2024). "However, the suppression of FoxQ1 inhibits invasion and metastasis through the reversal of epithelial–mesenchymal transition in bladder cancer." (PMID 36078038, 2022). "This strategy identified a large module of Luminal TFs, including known Luminal-associated TFs (e.g., FOXA1/GATA3/PPARG), as well as TFs with yet unexplored roles in Luminal bladder cancer biology (e.g., HES1, FOXQ1, ZBTB7C, MECOM, GRHL2/3, and TBX3)." (PMID 36944729, 2023).
colon cancer (10 papers, 2012 to 2024). "PGC using expO data revealed that breast, prostate and colon tumors had a strong association between FOXQ1 and Wnt related genes (t values>3 for AXIN2 and APCCD1)." (PMID 23555880, 2013). "FOXQ1 is another PI3K signaling and WNT target gene, and its overexpression of is associated with colon tumor formation and metastasis." (PMID 38609520, 2024). "The TCGA results indicated that SPIB, KRT24, PHLPP2, PLP1, BEST4, CA7, and C11orf86 were all downregulated, while KRT80, SLC39A10, AJUBA, FOXQ1, and CLDN1 exhibited upregulated levels in colon cancer." (PMID 32633726, 2020). "Similar to LEF1, other WNT-related genes found in our RNA-seq to be regulated by MYC such as FOXQ1 and LRP6, were also transcriptionally repressed upon MYC knockdown in colon cancer cells." (PMID 31623618, 2019). "Thus, FOXQ1-mediated activation of c-MYC signaling and polyamine synthesis is an intrinsic molecular phenotype of colon cancer." (PMID 36457036, 2022). "In order to validate the in silico analysis, we knocked down FOXQ1, using shRNA interference, and analysed the expression of genes which strongly correlated with FOXQ1 expression in colon cancer biopsy samples and EMT-related genes, which did not correlate with FOXQ1." (PMID 23555880, 2013).
ovarian carcinoma (8 papers, 2012 to 2025). A malignant neoplasm originating from the surface ovarian epithelium. "In ovarian cancer, the FOXQ1 gene is associated with a poorer prognosis, meaning higher levels of FOXQ1 expression often correlate with a worse outcome for patients." (PMID 41465326, 2025). "Moreover, NAC1 regulates the expression of over 700 genes in ovarian cancer, including FOXQ1, which is associated with increased mobility of tumor cells." (PMID 32412910, 2020). "Studies have shown that FOXQ1 promotes tumor progression in ovarian cancer both in vitro and in vivo." (PMID 41465326, 2025). "PARP1 disrupted the interaction of FOXQ1 and CHIP in ovarian cancer cells, which increased the protein levels of FOXQ1." (PMID 39777582, 2025). "The WNT/β-catenin pathway is activated by FOXQ1, which accelerates the development of ovarian cancer." (PMID 39223632, 2024). "In silico analysis revealed a significant co-up-regulation of NAC1 and FOXQ1 in ovarian carcinoma tissues." (PMID 32412910, 2020). "Given the potential role of FOXQ1 in cancer biology, the present study was undertaken to characterize its functional role in ovarian carcinomas." (PMID 23203039, 2012). "The data as demonstrated in this study warrants further investigation of FOXQ1 target-based therapies for advanced stage ovarian carcinomas." (PMID 23203039, 2012). "To this end, we analyzed gene expression levels in ovarian cancer tissues and cell lines and demonstrated a higher expression level of FOXQ1 in epithelial ovarian cancer cells than that in normal epithelial cells." (PMID 23203039, 2012). "This is the first report of FOXQ1 upregulation in ovarian carcinomas, and more importantly, this report demonstrated the expression of FOXQ1 is essential to maintain cell cycle progression and promote cellular motility and invasion of ovarian cancer cells." (PMID 23203039, 2012). "Taken together, these results suggest that FOXQ1 expression is essential to maintain cell proliferation, motility/invasion, and epithelial-mesenchymal transition phenotypes in ovarian cancer cells." (PMID 23203039, 2012). "In summary, FOXQ1 is overexpressed in both tissues and cell lines of epithelial ovarian cancers compared to their normal epithelial counterparts." (PMID 23203039, 2012). "Interestingly, TWIST1 has been reported to regulate DDR2 expression in ovarian cancer and was found to be a shared effector of FOXQ1 and SNAI1 in this study." (PMID 36713812, 2022). "Our observation that NAC1 and BCL6 activate FOXQ1 promoter activity via a positive, cooperative mechanism suggest that these molecules may be coordinately regulated in ovarian cancer." (PMID 32412910, 2020). "While studying the transcriptome regulated by NACC1, a gene that encodes the NAC1 protein and participates in the pathogenesis of ovarian cancer recurrence and chemoresistance, we found that FOXQ1 was significantly upregulated by NAC1 in ovarian high-grade serous carcinomas." (PMID 23203039, 2012). "Interestingly, the PARP inhibitor niraparib attenuated tumour growth in a mouse xenograft model with ovarian cancer cells expressing FOXQ1, suggesting that PARP inhibition may have the additional benefit of counteracting FOXQ1 in cancer." (PMID 39777582, 2025). "In ovarian cancer (OC), PARP1 stabilizes the protein level of Forkhead box Q1 (FOXQ1) through the E3 ubiquitin ligase Hsc70-interacting protein (CHIP)." (PMID 39223632, 2024). "We then used a human ovarian cancer cell line, SKOV3, which expressed a higher level of FOXQ1, as a cell model to investigate the biological effects of FOXQ1 by using RNA interference." (PMID 23203039, 2012).
pancreatic cancer (7 papers, 2010 to 2025). "Imputation analysis also revealed modest association at SNPs located near to or on the FOXQ1 gene suggesting it to be one of the causative genes for pancreatic cancer." (PMID 20686608, 2010). "In pancreatic cancer, for instance, the transcription factor Forkhead box Q1 (FOXQ1) directly activates LDHA transcription, thereby increasing lactate output and fueling tumor growth." (PMID 41152975, 2025). "FOXQ1 promotes pancreatic cancer cell proliferation, tumor stemness, invasion, and metastasis through regulation of LDHA-mediated aerobic glycolysis." (PMID 40141294, 2025). "Furthermore, the up-regulated expression of FOXQ1 has been correlated with tumor stem cell radio-resistance in pancreatic cancer." (PMID 35183223, 2022). "Interestingly, FOXQ1 overexpression in pancreatic cancer stem cells has been suggested to promote the resistance of cancer stem cells to radiotherapy." (PMID 35183223, 2022). "Furthermore, a recent study showed that FoxQ1 is overexpressed in pancreatic cancer, suggesting its role in pancreatic cancer tumorigenesis." (PMID 20686608, 2010). "FOXQ1 via promotes the transcription of Lactate dehydrogenase A (LDHA) and increases its expression in pancreatic cancer (PC)." (PMID 41347087, 2025).
cervical cancer (6 papers, 2016 to 2025). A primary or metastatic malignant neoplasm involving the cervix. "High expression of FOXQ1 enhances the migration and metastatic abilities of cervical cancer cells, promotes epithelial-mesenchymal transition (EMT), and decreases chemosensitivity." (PMID 40248198, 2025). "Previous study has demonstrated that miR-506 inhibits proliferation and EMT of cervical cancer cells by targeting FOXQ1, suggesting that the miR-506/FOXQ1 axis plays an important role in the pathogenesis of cervical cancer." (PMID 27999212, 2017). "Similarly, in cervical cancer tissues, a reduction in miR-506 levels has been observed, which is negatively correlated with FOXQ1 expression." (PMID 40248198, 2025). "Up-regulation of ENST00000420168, ENST00000564977 and down-regulation of TCONS_00010232 might stimulate FOXQ1 expression and suppress CASP3 expression in HPV-18 positive cervical cancer cell, which lead to HPV-induced proliferation and deficiency in apoptosis." (PMID 27363024, 2016).
glioma (5 papers, 2013 to 2024). A benign or malignant brain and spinal cord tumor that arises from glial cells (astrocytes, oligodendrocytes, ependymal cells). "In this study, we found both clinical and causal experimental evidence that aberrant FoxQ1 expression critically regulates the tumorigenicity of human glioma cells." (PMID 23383267, 2013). "FoxQ1 mRNA and protein were up-regulated in gliomas and negatively related to the NRXN3 expression (r = −0.373, P = 0.042)." (PMID 23383267, 2013). "In the present study, we showed that FoxQ1 expression was higher in glioma specimens than the normal tissues, whereas NRXN3 expression was lower in glioma specimens." (PMID 23383267, 2013). "Together, our results indicated that FoxQ1 enhances the ability of glioma cells proliferation and migration by down-regulation of NRXN3 expression in vitro." (PMID 23383267, 2013). "To provide direct evidence that FoxQ1 affect the malignant phenotype by down-regulation of NRXN3 in glioma cells, we transfected NRXN3 shRNA into FoxQ1-shRNA2 to rescue the NRXN3 expression and established the stable clone (NRXN3-rescue)." (PMID 23383267, 2013). "Next, we tested the function of FoxQ1/NRXN3 interaction by assessing their roles in glioma cells biological behaviors." (PMID 23383267, 2013). "Inhibition of FoxQ1 in glioma cells by transfection of FoxQ1 shRNA significantly up-regulated NRXN3 expression and reduced the ability of proliferation and migration in glioma cells, whereas overexpression of a FoxQ1 expression vector did the opposite." (PMID 23383267, 2013). "We sought to determine the molecular mechanism by which FoxQ1 promote glioma development by down-regulating NRXN3 expression." (PMID 23383267, 2013). "Compared with the G1 + G2 grade, the FOXQ1 expression level in the G3 + G4 grade was higher in bladder urothelial carcinoma, brain lower-grade glioma, and liver hepatocellular carcinoma but lower in stomach adenocarcinoma and uterine corpus endometrial carcinoma." (PMID 36118871, 2022). "Therefore, our results suggest that NRXN3 expression negatively related to FoxQ1 expression in human glioma tissues." (PMID 23383267, 2013). "FoxQ1 seemed to crucially regulate NRXN3 expression through direct interaction with NRXN3 promoter, as mutation of FoxQ1 binding sites significantly up-regulated NRXN3 promoter activity in glioma cells." (PMID 23383267, 2013). "FoxQ1 expression negatively related to the NRXN3 expression in glioma specimens." (PMID 23383267, 2013). "FoxQ1 promotes glioma cell proliferation and migration by down-regulation of NRXN3 expression." (PMID 23383267, 2013). "Our present results indicated that FoxQ1 was also high expression in gliomas." (PMID 23383267, 2013). "Furthermore, we performed transwell assay to assess the function role of FoxQ1/NRXN3 in glioma cells migration." (PMID 23383267, 2013). "The results indicated FoxQ1 mRNA expression was up-regulated in glioma specimens." (PMID 23383267, 2013). "We investigate FoxQ1 expression in gliomas and the role of FoxQ1 during tumorgenesis." (PMID 23383267, 2013). "Thus, our work indicated that FoxQ1 regulates gliomas development by down-regulation of NRXN3 expression." (PMID 23383267, 2013). "Finally, the FoxQ1 expression levels directly affected the glioma cells proliferation and migration in a NRXN3-dependent manner both in vitro and in vivo." (PMID 23383267, 2013). "Furthermore, FoxQ1 expression negatively related to NRXN3 expression in human glioma tissues." (PMID 23383267, 2013). "For instance, FOXQ1 and FOXF2 were highly expressed in glioma, FOXF1 in LUAD, and GATA4 in CHOL and LIHC, all consistent with previous studies." (PMID 39345334, 2024). "To determine the FoxQ1 and NRXN3 expression levels in glioma cells lines and normal human astrocytes cells, we examined the FoxQ1 and NRXN3 expression in Hs683, U-87MG, SW1088, LN-229 and NHA cells by RT-qPCR and Western blot." (PMID 23383267, 2013).
glioma (continued). "The results showed that higher expression of FoxQ1 mRNA and protein was evident in Hs683, U-87MG, SW1088 and LN-229 glioma cells than the normal human astrocytes." (PMID 23383267, 2013). "The relation between FoxQ1/NRXN3 expression and survival of patients with gliomas need to be clarified in future study." (PMID 23383267, 2013). "In conclusion, we have shown that FoxQ1 was highly expressed, whereas NRXN3 was lowly expressed in gliomas." (PMID 23383267, 2013). "Of more importance, we found that FoxQ1 directly regulated NRXN3 expression and glioma proliferation and migration." (PMID 23383267, 2013). "Reverse transcription quantitative real-time PCR (RT-qPCR) and Western blot were used to determine the FoxQ1 and Neurexins 3 (NRXN3) expression in gliomas." (PMID 23383267, 2013). "Thus, we hypothesized that FoxQ1 promotes glioma development by downregulation of NRXN3 expression." (PMID 23383267, 2013). "FOXQ1 expression participated in the activation of the epithelial–mesenchymal transition pathway, early estrogen response pathway, RAS signaling pathway, apoptosis pathway, and UV response pathway in brain lower-grade glioma." (PMID 36118871, 2022). "Therefore, FoxQ1 overexpression contributes directly to NRXN3 underexpression in gliomas and seems to be critical for glioma development." (PMID 23383267, 2013). "However, whether FoxQ1 expression contributes to glioma development and progression is not known." (PMID 23383267, 2013).
prostate carcinoma (5 papers, 2019 to 2021). A carcinoma that arises from epithelial cells of the prostate gland. "In prostate cancer, BCL11A was significantly down-regulated when FOXQ1 loss its function, and led to decreased proliferation, invasion and increased apoptosis in prostate cancer cells." (PMID 31654056, 2019). "In prostate cancer, FOXQ1 regulated the expression of BCL11A/MDM2 to promote cell proliferation." (PMID 33748185, 2021). "Interestingly, TWIST1 was not significantly correlated with stromal score in prostate cancer samples, while FOXQ1 was not significantly correlated with stromal cell abundance in colorectal and lung adenocarcinoma." (PMID 31780722, 2019).